CTLA4 (cytotoxic T-lymphocyte associated protein 4)
Diseases named in the same sentence as CTLA4 in open-access papers (continued):
Sharing a sentence is not in itself a finding about the gene and the disease.
melanoma (continued). "Multiple follow-up clinical trials addressed the activity of combination therapies targeting PD-1 and CTLA-4 vs. monotherapy in advanced melanoma patients." (PMID 32117271, 2020). "Anti-CTLA-4 antibodies, such as Ipilimumab, can induce successful anti-cancer therapeutic effects especially in melanoma patients." (PMID 32781690, 2020). "Long-term interferon signals were observed to coordinate both PD-L1-dependent and PD-L1-independent resistance to ICB-involved therapy such as radiation plus anti-CTLA-4 in melanoma mouse models and patients." (PMID 33344447, 2020). "Ipilimumab is a fully humanized IgG1 subclass monoclonal antibody against CTLA-4 and was approved for melanoma therapy by the US Food and Drug Administration in 2011." (PMID 31911758, 2020). "Patient cohort Mel-CTLA4-A was used as a discovery cohort for anti-CTLA-4 and consists of 10 melanoma patients selected based on an equal distribution of responders and non-responders." (PMID 33427690, 2020). "Similar results were obtained when feces from melanoma patients treated with ipilimumab were transplanted into germ-free mice, which resulted in the induction of a marked response to anti-CTLA-4 and decreased tumor growth." (PMID 33062956, 2020). "Expression of MAGE-A genes and other CTAg in primary melanoma specimens was correlated with resistance to anti-CTLA-4 immune checkpoint therapy." (PMID 32133047, 2020). "The combination of anti-PD-1/PD-L1 and anti-CTLA-4 are also being tested in the clinic for stage III/IV melanoma patients." (PMID 32092958, 2020). "Progress in immunotherapy and the development of T cell ICIs such as CTLA-4 and PD-1 inhibitors have further limited the use of IL-2 as a treatment for melanoma patients in high doses." (PMID 32580338, 2020). "In peripheral blood, a gene signature of 15 differentially expressed genes, which includes MYC and CDK2, is predictive and prognostic to anti-CTLA4 immunotherapy treatment and 1 year overall survival in melanoma patients." (PMID 31820036, 2020). "Elevated pre-treatment CRP level was also shown to be related to poor OS in both anti-PD-1 and anti-CTLA-4 melanoma therapies." (PMID 32992737, 2020). "The combination therapy with anti-cytotoxic T-lymphocyte-associated antigen-4 (CTLA-4) antibody and anti-PD-1 antibody was approved for use for unresectable malignant melanoma by the FDA in America in 2015." (PMID 32435885, 2020). "In this framework, Ipilimumab, a CTLA-4 inhibitor, was demonstrated to improve survival rates in melanoma patients." (PMID 32722205, 2020). "Previous reports have shown that anti-CTLA-4 treatment leads to a significant broadening of CD8+ T-cell responses specific for melanoma and an increased diversity of T cells in blood after CTLA-4 blockade." (PMID 32127601, 2020). "A previous study showed that immunotherapy increases treatment-related necrosis in melanoma cases, especially when using ipilimumab, a drug targeting CTLA-4." (PMID 33339421, 2020). "We evaluate these signatures in The Cancer Genome Atlas Program (TCGA) Pan-Cancer cohort and four cohorts comprising patients with melanoma, lung, and head and neck cancer treated with anti-PD-1 or anti-CTLA-4 therapies." (PMID 32858956, 2020). "In support of this, we detect a fivefold difference in the production of the T cell activation marker IFN-ɣ23 37–39 in melanoma tumors isolated from brain vs flank of ISV + α-CTLA-4 treated mice." (PMID 32690669, 2020). "In 2011, the first ICI, ipilimumab, an immune cell cytotoxic T lymphocyte-associated protein-4 (CTLA-4)-targeting monoclonal antibody, was approved by the FDA to treat patients with advanced melanoma based on two pivotal phase III clinical trials." (PMID 33268350, 2020). "Following ISV + α-CTLA-4, we observed distinct patterns of immune activation and inflammatory response at melanoma sites in the flank and brain." (PMID 32690669, 2020).
melanoma (continued). "The combination of RT and dual immune checkpoint blockade of CTLA4 and PDL1 has been linked to improved outcomes and tumor regression in patients with melanoma." (PMID 32090113, 2020). "Melanoma is sensitive to immune checkpoint inhibitors (such as anti-CTLA4 and anti-PD1 monoclonal antibodies) and small-molecule targeted drugs (such as BRAF inhibitors and MEK inhibitors)." (PMID 32709086, 2020). "In melanoma mouse model it was shown that raising tumor pH with sodium bicarbonate would slow the growth of Yumm1.1 melanoma and it enhanced anti-PD-1 or anti-CTLA-4 therapy efficacy." (PMID 32509589, 2020). "In particular, higher quantities of melanoma-specific antibodies were found in the serum of patients responding to CTLA-4 or PD-1 inhibition." (PMID 32457745, 2020). "This phenomenon was first reported in ∼10% of patients with advanced melanoma during anti‐CTLA‐4 therapy." (PMID 32997401, 2020). "This is consistent with a model in which there is very little de novo difference between the immune microenvironments of immunologically cold melanoma inside or outside of the brain prior to ISV + α-CTLA-4 treatment." (PMID 32690669, 2020). "There are currently three main anti-CTLA-4 antibodies under preclinical and clinical trials for the treatment of melanoma: Tremelimumab, Ipilimumab (Yervoy), and BCD-145." (PMID 32092958, 2020). "For this study, serum samples of 113 melanoma patients were collected at baseline and tested with a soluble CTLA-4 specific ELISA." (PMID 33643899, 2020). "These drugs include ipilimumab (Yervoy®), an anti-CTLA-4 monoclonal antibody indicated for the treatment of advanced melanoma or azacitidine (Vidaza®), a chemotherapy drug used in the treatment of some types of myelodysplastic syndromes and leukemia." (PMID 31880288, 2020). "We demonstrate an endogenous tumor-specific antibody response following a therapeutic regimen that combines RT + IT-IC + anti-CTLA-4 for the treatment of a syngeneic B78 melanoma." (PMID 32849544, 2020). "Ipilimumab is a CTLA-4 inhibitor approved for melanoma, renal cell carcinoma, microsatellite instability–high, or mismatch repair deficiency colorectal cancer." (PMID 32988414, 2020). "We further characterized the efficacy of SB-3CT, in combination with anti-PD-1 and/or anti-CTLA4 treatment in mouse models with melanoma and lung cancer." (PMID 32988398, 2020). "Therapeutic targeting of CTLA-4 has resulted in the first demonstrable evidence of anti-tumour regression following selective modulation of a T-cell co-inhibitory pathway in melanoma." (PMID 32157213, 2020). "Serum was collected from mice bearing B78 melanoma tumors before, during, and after RT + IT-IC + anti-CTLA-4 treatment in order to determine the time course of the anti-tumor adaptive humoral response." (PMID 32849544, 2020). "Immunotherapy based on cytotoxic T lymphocyte-associated antigen 4 (CTLA4), programmed death-1 (PD-1), and programmed death ligand-1 (PD-L1) inhibitors has emerged as an effective treatment in melanoma and non–small-cell lung carcinoma." (PMID 32986017, 2020). "The immune system plays a pivotal role in melanoma therapy, and specific immune therapies have been developed, such as anti-CTLA4 and anti-PD1-based immune therapies." (PMID 32013263, 2020). "For those patients who received dual PD-1 and CTLA-4 inhibitors, one had melanoma and one had NSCLC." (PMID 32733645, 2020). "A large body of experimental evidences confirmed the beneficial role of CTLA-4 inhibition in increasing immune recognition and elimination also of poorly immunogenic murine melanoma and prostate cancers." (PMID 33162990, 2020). "In a mouse bone metastasis model, treatment with an anti-CTLA-4 antibody decreased the skeletal tumor burden in mice inoculated with B16 melanoma cells." (PMID 32326073, 2020).
melanoma (continued). "We followed the staining method of mMDSCs described by Kitano and colleagues showing that peripheral mMDSC proportion correlated with overall survival in melanoma patients treated with ipilimumab (monoclonal antibody against CTLA-4)." (PMID 33370317, 2020). "There is an increased frequency of Th1-like T cells in melanoma samples treated by anti-CTLA-4 compared with those treated by anti-PD-1 antibodies." (PMID 33268350, 2020). "Antibodies that block CTLA-4, PD-1, and PD-L1 are widely used for the treatment of various cancers, including melanoma." (PMID 33256089, 2020). "Checkpoint inhibitors, anti-CTLA-4 and anti-PD-1 are approved in most of the European countries as therapies for melanoma, but still prediction markers for efficacy lack." (PMID 32509589, 2020). "B78 melanoma brain tumors in ISV + α-CTLA-4 treated mice at death were analyzed by IHC to evaluate immune infiltrate." (PMID 32690669, 2020). "The pharmacologic inhibition of protein-serine O-palmitoleoyltransferase porcupine (PORCN), an enzyme necessary for Wnt ligand secretion, synergistically suppressed melanoma progression when combined with anti–CTLA-4 antibody treatment." (PMID 33171792, 2020). "The combination of nivolumab, a checkpoint inhibitor that targets PD-1, and ipilimumab, the CTLA-4 blockade drug in the treatment of naïve advanced melanoma, has shown significantly increased progression-free survival compared with ipilimumab alone." (PMID 33216822, 2020). "A phase Ib trial investigating Imlygic in combination with a CTLA-4 inhibitor, ipilimumab, was conducted in patients with untreated late stage melanoma and achieved positive results." (PMID 33207653, 2020). "For this, we labeled B16 cells using serum from mice rendered disease-free from a B78 melanoma tumor by treatment with RT + IT-IC + anti-CTLA-4 and demonstrating immune memory by rejection at D90 of re-implantation with B78." (PMID 32849544, 2020). "In one study of the 64 melanoma patients receiving anti-CTLA-4 therapy, only 11 patients showed long-term benefit and 14 patients showed little to no benefit." (PMID 32944086, 2020). "Different studies have correlated the elevation of circulating MDSC numbers with poor clinical responses to anti-cytotoxic T lymphocyte antigen-4 (CTLA-4) and anti-PD-1 immunotherapies in advanced melanoma patients." (PMID 32824655, 2020). "There are several reports on combination therapies in patients with malignant melanoma treated with ipilimumab targeting the CTLA-4 checkpoint, as this was already approved in 2011 for the treatment of metastatic melanoma." (PMID 32867046, 2020). "An enrichment in Tcf7 gene was also reported in tumor-infiltrating cells from melanoma patients after anti-PD-1/anti-CTLA-4 therapies." (PMID 32707692, 2020). "The immunotherapies also available for advanced-stage melanoma are based on CTLA-4 and PD-1 blockers, which confer a survival benefit and more durable responses, compared to targeted therapies." (PMID 33072757, 2020). "In vivo, the combination of GSK503, an Ezh2 inhibitor, with anti-CTLA-4 or IL-2 proved to be more efficient than monotherapies in the treatment of melanoma." (PMID 32867025, 2020). "Currently, there are three agents approved for advanced melanoma treatment: ipilimumab (anti-CTLA-4; since 2011), nivolumab, and pembrolizumab (both anti-PD-1; since 2014)." (PMID 32517213, 2020). "We collected clinical characteristics of total 318 patients diagnosed with melanoma and treated with anti‐CTLA‐4 or anti‐PD1 therapy from previous studies." (PMID 32969604, 2020). "In melanoma patients treated with ICIs including anti‐CTLA4‐antibody and anti‐PD‐1 antibody, high pretreatment levels of serum sPD‐L1 were associated with an increased likelihood of progressive disease in patients treated with ICIs." (PMID 33108686, 2020).
melanoma (continued). "Immunotherapies against immune checkpoints programmed cell death protein 1 (PD-1) and cytotoxic T-lymphocyte-associated protein 4 (CTLA-4), aimed to awake the immune system that will eliminate the tumor, has proven successful in a subset of melanoma patients." (PMID 32391428, 2020). "Pseudoprogression has been reported, especially after therapy with CTLA-4 inhibitors in patients with melanoma, and less frequently in other tumor types (possibly in less than 5% of patients with other diseases, including NSCLC and lymphoma)." (PMID 32722205, 2020). "MUC16 mutation was associated with improved OS and response rates in anti-PD-1/PD-L1–treated patients with NSCLC, and this finding was verified in the independent melanoma cohort treated with anti-CTLA-4." (PMID 32845327, 2020). "One patient with stage IV-M1d melanoma who previously progressed on anti-PD-1 and anti-CTLA-4 checkpoint blockade achieved a durable PR according to iRECIST criteria (patient myDC-04 in Table A1)." (PMID 33182610, 2020). "In this regard, in a prospective analysis of melanoma patients treated with CTLA-4 and radiation, a subset of patients benefited from the combinatorial therapy." (PMID 31467431, 2020). "Comparable findings concerning TCR repertoire dynamics and clinical outcome with anti-CTLA-4 and anti-PD-1 targeting therapy were reported in advanced melanoma patients." (PMID 32325898, 2020). "In conclusion, ICI antibodies directed against CTLA-4 or PD-1 and PD-L1 have shown significant activity in several solid cancers, most notably, melanoma and NSCLC and in some hematological neoplasms, in particular classical HL." (PMID 32443877, 2020). "Although at higher risk of important immune-related toxicity, the combined inhibition of CTLA-4 and PD-1 signaling, using ipilimumab and nivolumab, has shown increased clinical efficacy in melanoma, kidney and lung cancer." (PMID 32727102, 2020). "Scientists studying the family of melanoma antigens found that CTLA-4 inhibitors enable TNBC patients with MAGE-A (melanoma associated antigen A) expression to achieve a greater immune response during treatment." (PMID 33033520, 2020). "Patients affected by non-small cell lung cancer or melanoma were treated with anti-CTLA-4, anti-PD-1/PD-L1 or combinations of both." (PMID 33023239, 2020). "(This morbidity is similar to what is seen in greater than 50% of patients with melanoma who experience at least grade 3 toxicity with PD-1 and CTLA-4 antibody combination clinically and often require dose reductions or permanent discontinuations)." (PMID 32599852, 2020). "Exploiting the different mechanisms that impair T cell response, co-blockade of CTLA-4 and PD-1 (Ipilimumab + Nivolumab) revealed additional anti-tumor efficacy but also high levels of side effects in treatment of melanoma." (PMID 32714324, 2020). "S-100 protein and LDH have been reported as early prognostic markers for response and overall survival in melanoma patients treated with anti-PD-1 or combined anti-PD-1 plus anti-CTLA-4 antibodies." (PMID 32631431, 2020). "In fact, the very successful combination therapy in malignant melanoma patients using anti-PD-L1 plus anti-CTLA-4 antibodies was reported to block inhibitory receptors as well as Treg functions." (PMID 32226027, 2020). "Both of the two CTLA-4 antibodies are currently being studied in over 300 clinical trials involving patients with malignant melanoma." (PMID 33036192, 2020). "Several clinical trials of drugs that block CTLA-4 have been conducted in advanced melanoma with concurrent radiotherapy." (PMID 33216822, 2020). "Monoclonal antibodies blocking PD-1 and CTLA-4 immunological checkpoints lead to durable tumor responses in a considerable number of advanced melanoma patients." (PMID 33262949, 2020). "In mice models of melanoma, CTLA-4 blockade increases the intratumor effector T cells/Tregs ratio, through fragment crystallizable (Fc)-gamma receptor (FcγR)-dependent mechanism." (PMID 33036192, 2020).
melanoma (continued). "Ipilimumab, a monoclonal antibody against CTLA-4, was the first inhibitor developed for the treatment of patients with stage IV melanoma." (PMID 32260561, 2020). "Following the success of PD-1 and CTLA-4 checkpoint inhibitors in melanoma, attention has turned to other checkpoint proteins such as IDO1." (PMID 32090113, 2020). "When applying these four genomic clusters to two anti-CTLA-4 treated melanoma cohorts, cluster 4 (MSIhigh, SCNAhigh, mTMBlow) showed the lowest rate of clinical benefit and the shortest OS." (PMID 32325898, 2020). "Pharmacological inhibition of IDO by 1-methyl-tryptophan (1MT) combined with anti-CTLA-4 resulted in rejection of established tumors and resistance to secondary challenge in mice inoculated with B16 melanoma." (PMID 33072086, 2020). "A recent phase 2 trial with DCs combined with anti-CTLA-4 mAbs showed tolerability and an encouraging objective response rate (38%) in pre-treated advanced melanoma patients." (PMID 31980913, 2020). "Tremelimumab is a fully human IgG2 isotype monoclonal antibody used against CTLA-4 and is under investigation as a treatment for several cancers, including melanoma, mesothelioma, and NSCLC." (PMID 32580338, 2020). "The low methylation level of the CTLA-4 promoter was associated with a weak response to immune checkpoints inhibitors (both anti-CTLA-4 and anti-PD-1) and overall survival of melanoma patients." (PMID 32517213, 2020). "Monotherapy and combined therapy with CTLA-4 antibodies (ipilimumab) and PD-1 antibodies (pembrolizumab, nivolumab) have been shown to elicit a positive response against melanoma." (PMID 32429485, 2020). "Advanced melanoma patients that respond to anti-CTLA-4 therapy have higher levels of circulating memory CD4+ and CD8+ T cells at baseline." (PMID 32998446, 2020). "To further elucidate the magnitude of the anti-melanoma response observed in Aire−/− mice, we performed RNAseq in tumors from Aire+/+ and Aire−/− mice treated with anti-CTLA4." (PMID 32641748, 2020). "The first checkpoint antibody approved by the FDA was ipilimumab (CTLA-4 inhibitor) for the treatment of melanoma." (PMID 32645977, 2020). "The study included pre-treatment melanoma biopsies from 36 patients subsequently treated with anti-PD-1 (17/36, 47%) or combination (anti-PD-1 plus anti-CTLA-4) immunotherapy (19/36, 53%)." (PMID 33202676, 2020). "Immunotherapy of advanced melanoma with PD-1 and PD-L1 blocking antibodies as well as CTLA-4 antibodies has become state of the art in the clinics alongside targeted therapies." (PMID 32861198, 2020). "In that respect, a recent study on melanoma patients analyzed biopsies derived from patients who initially responded to either anti-PD-1 or anti-PD-1 plus anti-CTLA-4 mAb." (PMID 32727102, 2020). "Pembrolizumab, nivolumab and nivolumab in combination with iIpilimumab (anti-CTLA-4 inhibitor) have been approved by FDA for treatment of melanoma." (PMID 32092958, 2020). "In one study, when a melanoma cell line was treated with wnt3a, CTLA4 was the most up-regulated gene, which was proposed to represent a mechanism of immune evasion." (PMID 32835228, 2020). "NLR is a marker for the general immune response to various stress stimuli, and it is shown to predict outcome among NSCLC and melanoma patients treated with PD-1 inhibitors, and CTLA-4 antibodies." (PMID 31952311, 2020). "In the clinic, combination of bevacizumab, a humanized monoclonal antibody targeting VEGF, with ipilimumab (anti-CTLA-4) also demonstrated favorable therapeutic outcomes in patients with melanoma compared to ipilimumab treatment alone." (PMID 33217955, 2020). "CSF-1R inhibitor showed tumor regression when combined with anti-PD-1 or CTLA-4 antibody and gemcitabine in pancreatic cancer models and showed synergy with adoptive cellular therapy in melanoma cell models." (PMID 35582437, 2020).